COL1A2 (collagen type I alpha 2 chain)
Diseases named in the same sentence as COL1A2 in open-access papers (continued):
Sharing a sentence is not in itself a finding about the gene and the disease.
renal fibrosis (9 papers, 2013 to 2025). A final common manifestation of a wide variety of chronic kidney diseases characterized by glomerulosclerosis and tubulointerstitial fibrosis. "Confirming our dose range experiments, X203 reduced AKI-induced loss of kidney mass, limited renal fibrosis, and improved renal function while lowering inflammatory (Tnfα, Il6, Ccl2, Ccl5, Il1β), fibrosis (Col1a1, Col1a2, Col3a1, Fn1, Acta2) and tubular damage (Kim1, Ngal) markers." (PMID 36470928, 2022). "Next, we evaluated the expression of three genes that are increased in renal fibrosis [collagen 1A2 (COL1A2), fibronectin 1 (FN1), and α-smooth muscle actin (α-SMA)]." (PMID 36499744, 2022). "It has been reported that the upregulation of COL1A2 in diabetic kidney disease (DKD) can lead to increased renal fibrosis." (PMID 35923621, 2022). "COL1A2, collagen type I α2 chain, is closely positively related to the progression of renal fibrosis in DN." (PMID 35592524, 2022). "Similarly, renal fibrosis was increased in all kl/kl mice and mRNA expression of markers of fibrogenesis such as Timp1, Col1a2 and Fn1 were elevated in kl/kl kidneys independently of the presence of FGFR4." (PMID 31575945, 2019). "Furthermore, the mRNA expression of the renal fibrosis-related genes Col1a2, Fn1, and Tgfb1 were all significantly increased in Pkd1 miR Tg mice (p < 0.05) compared with wild-type mice." (PMID 30585217, 2018). "A more reliable and consistent marker of renal fibrosis is COL1A2." (PMID 24040012, 2013). "The injection of an miR−122−5p mimic promoted renal fibrosis and upregulated COL1A2 and FN1, whereas an miR−122−5p inhibitor suppressed renal fibrosis and downregulated COL1A2 and FN1." (PMID 36499744, 2022). "Moreover, RNA-seq analysis revealed that the SVF-treated group exhibited significantly reduced expression levels of Fn1, Col1a2, and Acta2, suggesting that SVF may attenuate renal fibrosis progression." (PMID 40432888, 2025).
head and neck cancer (8 papers, 2014 to 2025). A primary or metastatic malignant neoplasm affecting the head and neck. "In some studies, by comparing three separate comprehensive gene expression omnibus (GEO) databases, researchers claimed that overlapping differentially expressed genes like SPP1, POSTN, and COL1A2 could be used as potential diagnostic indicators of head and neck carcinoma." (PMID 33134377, 2020).
intracranial aneurysms (8 papers, 2012 to 2022). "In addition, COL1A2 overexpression was a significant risk factor for intracranial aneurysm susceptibility." (PMID 36057263, 2022). "An increased expression of the newly identified stroke genes Il6ra, Il6st, S100a4, Stat1, and Stat2, but also the known genes Col1a1, Col1a2, Col3a1, has been implicated in blood vessel remodeling and contributes to vascular rarefaction, leakage, and intracranial aneurysms." (PMID 24672479, 2014). "COL1A1 and COL1A2 were shown to be direct targets of miR-513b-5p in patients with intracranial aneurysms." (PMID 36327243, 2022). "In this study, we investigated the association of rs42524 in the alpha-2 type I collagen (COL1A2) gene, which has been identified as a risk variant for intracranial aneurysm, with nAMD and PCV in a Han Chinese population." (PMID 22815632, 2012). "Collagen-type I alpha 1 chain (COL1A1) and COL1A2 are abnormally expressed in intracranial aneurysm (IA), but their mechanism of action remains unclear." (PMID 34290266, 2021). "COL1A2, COL3A1, COL5A2 are a group of collagen genes in which mutations are associated with several connective diseases such as the involvement of COL3A1 mutations in intracranial aneurysms and Ehlers-Danlos syndrome type IV with aortic and arterial aneurysms." (PMID 24079748, 2013).
myocardial infarction (8 papers, 2012 to 2024). Gross necrosis of the myocardium, as a result of interruption of the blood supply to the area, as in coronary thrombosis. "The collagen1a2 (Col1a2) transgenic mouse was used to assess TAM‐induced recombination in vivo in cardiac fibroblasts followed by myocardial infarction (MI)." (PMID 38291801, 2024). "The heart proteins ADD3, PTGIS, and COL1A2 are candidates for hypertension and myocardial infarction." (PMID 35259090, 2022). "However, Col1a2 Cre has recently been applied successfully to target fibroblasts during myocardial infarct healing, and in future, this approach will provide a means for testing the importance of Hsd11b1 in fibroblasts, and other mesenchymal cells, post MI." (PMID 28522730, 2017). "Furthermore, many vascular abnormalities, including stroke, myocardial infarction, and IA, have been found to be due to defects in COL1A2." (PMID 22815632, 2012). "Additionally, the study identified potential candidate genes, such as COL1A2 and BCL6, which interact with PPP2R3A and are also believed to play a role in the progression of myocardial infarction and hypertrophic cardiomyopathy or in tumor development." (PMID 37868783, 2023).
osteosarcoma (8 papers, 2016 to 2024). A usually aggressive malignant bone-forming mesenchymal neoplasm, predominantly affecting adolescents and young adults. "In the high TELscore group, LRP1, ITGB1, IBSP, COL1A1, and COL1A2 were the most active signaling pathways of others in osteosarcoma cells." (PMID 39980969, 2024). "On the molecular level, a reduced level of COL1A2 was inversely correlated with osteosarcoma proliferation and migration under cisplatin restriction." (PMID 36428591, 2022). "According to our results, the expression of FN1, COL1A1, and COL1A2 were downregulated in osteosarcoma and Ewing's sarcoma, which often act as oncogenes, suggesting that they were more likely to play roles of antioncogene in osteosarcoma and Ewing's sarcoma." (PMID 35578666, 2022). "SERPINE2 may drive self-proliferation and drug resistance in osteosarcoma, and has poor prognosis for patients with bladder and ovarian cancer with high COL1A2 expressions." (PMID 36428591, 2022). "Our findings revealed the common oncogenic genes such as FN1, COL1A1, and COL1A2, which may act as antioncogene by enhancing cisplatin sensitivity in osteosarcoma cells, and pathways were both in osteosarcoma and Ewing's sarcoma." (PMID 35578666, 2022). "Among 12 hub genes, hub genes FN1, COL1A1, and COL1A2 may involve in the development of osteosarcoma and Ewing's sarcoma." (PMID 35578666, 2022). "Besides COL1A2, the ferritin light chain (FTL) expression was shown in association with the response to chemotherapy and contributed to the proliferation, migration, and invasion of osteosarcoma cells." (PMID 36428591, 2022). "Our western blot confirmed that FN1, COL1A2, and COL1A1 were reduced expression both in osteosarcoma and Ewing's sarcoma tissues compared to normal tissues." (PMID 35578666, 2022). "Our RT-qPCR results showed that FN1, COL1A2, COL1A1, and ADAMTS2 were downregulated both in osteosarcoma and Ewing's sarcoma tissues compared to normal tissues." (PMID 35578666, 2022). "Common key genes both in osteosarcoma and Ewing's sarcoma were identified, such as FN1, COL1A2, and COL1A1, which may act as antioncogene by enhancing cisplatin sensitivity in osteosarcoma cells and require further investigation." (PMID 35578666, 2022). "Finally, we tested the impact of MC3353 on the expression of three genes [collagen type I alpha 2 chain (COL1A2), alkaline phosphatase (ALP), and osteocalcin (OCN)] involved in osteosarcoma differentiation processes as well as on matrix mineralization in Saos-2 cells." (PMID 31060628, 2019). "Our GO enrichment analysis results showed that FN1, COL1A2, and COL1A1 were significantly enriched in the extracellular matrix, protease binding, and so on, indicating that the three genes could play a critical role in the development of osteosarcoma and Ewing's sarcoma." (PMID 35578666, 2022).
cardiomyopathy (7 papers, 2019 to 2025). A disease of the heart muscle or myocardium proper. "mRNA microarray analysis was also employed to interrogate the underlying molecular basis for cardiomyopathy in Col1a2−/− mice, which showed 225 upregulated and 249 downregulated genes in the heart due to the loss of Col1a2." (PMID 37681905, 2023). "Accordingly, RT-qPCR analysis confirmed that miR199a-5p reduced the expression of the cardiomyopathy marker genes nppa and Mhy7 as well as the genes expression of the collagen marker Col1a1, Col1a2, and Col3a1." (PMID 38956062, 2024). "Given the baseline cardiomyopathy and augmented fibrosis observed in germline Col1a2 gene-deleted mice, we then employed a conditional Col1a2 deletion strategy to investigate the acute effects of fibrosis inhibition within the heart during disease stimulation." (PMID 37681905, 2023). "This slight increase in COL1A2 and IGF1 in ADAR2-/- mouse heart tissues indicated that ADAR2 is not the core factor related to cardiomyopathy." (PMID 31039163, 2019).
COVID-19 (7 papers, 2021 to 2023). A disease caused by infection with severe acute respiratory syndrome coronavirus 2. "In fact, overexpression of some genes involved in these processes, such as COL1A2 and COL3A1, were observed in both COVID-19 and UIP/IPF." (PMID 36405615, 2022). "Specifically, signatures of plasma cells (IGHG3, IGKC, IGHM, JCHAIN, IGHG2, IGKV4-1, IGLV3-1, IGHA1), activated fibroblasts (COL1A1, COL1A2, COL3A1), inflammatory cytokines (CXCL9, CCL18) and complement factors (C1QB, C1QC) dominated the DE genes for the COVID-19 lung sections." (PMID 37858234, 2023).
diabetes (7 papers, 2012 to 2025). "Diabetes was found to contribute to the development of tendinopathy through the downregulation of Scx, Mkx, Col1a1, Col1a2, and Bgn, and the upregulation of Col1a1, Scx, and Dcn contributed to the control of tendinopathy." (PMID 34737845, 2021).
skin aging (7 papers, 2017 to 2024). The gradual irreversible changes in structure of skin that occur as a result of the passage of time.. "Pure inotodiol/inotodiol concentrate could also modulate the synthesis of collagen and hyaluronic acid by controlling COL1A2 and HAS2/3 expression, which implies a crucial role for inotodiol/inotodiol concentrate in the prevention of skin aging." (PMID 37628993, 2023). "Moreover, pure inotodiol/inotodiol concentrate could also modulate the synthesis of collagen and hyaluronic acid by controlling COL1A2 and HAS2/3 expression, which implies a crucial role for pure inotodiol/inotodiol concentrate in the prevention of skin aging." (PMID 37628993, 2023).
arthrochalasia EDS (6 papers, 2020 to 2025). "Arthrochalasia Ehlers-Danlos Syndrome (aEDS), also known as Ehlers-Danlos Syndrome type VII, is an autosomal dominant condition caused by heterozygous mutations in the COL1A1 and COL1A2 genes, which normally encode the pro-alpha-1 and pro-alpha-2 chains of type 1 collagen." (PMID 36237549, 2022).
Cirrhosis (6 papers, 2011 to 2025). A chronic disorder of the liver in which liver tissue becomes scarred and is partially replaced by regenerative nodules and fibrotic tissue resulting in loss of liver function. "Considering that COL1A2 is a collagen, we performed a correlation analysis between SOX4, LGALS3, SERPINE2, CD52, LPXN, and MPP6 and the progression of cirrhosis." (PMID 39194690, 2024). "Taken together, it implies that PPIs among COL1A1, COL1A2, VWF and LUM may participate in the induction of cirrhosis and play roles in the progression from cirrhosis to HCC." (PMID 21526182, 2011). "CXCR4 (AUC = 0.941), COL1A2 (AUC = 0.919), CCR7 (AUC = 0.878), COL1A1 (AUC = 0.853), CXCL12 (AUC = 0.848), and CXCL8 (AUC = 0.828) had similar AUC values, demonstrating that the identified hub genes exhibited a reliable discriminatory capacity as potential biomarkers for cirrhosis." (PMID 41223189, 2025).
diabetic nephropathy (6 papers, 2022 to 2026). "Previously, COL1A2 upregulation has been measured in both mice with diabetic nephropathy and HK2 cells treated with HG19." (PMID 36463298, 2022). "Recently studies have shown that upregulated COL1A2 level is related to the progression of diabetic nephropathy and suggested that miRNAs targeting COL1A2 could be a potential therapy strategy." (PMID 39872314, 2024). "Our study identifies COL1A2, CD163, FN1, and CCL2 as key molecular signatures involved in the immunoinflammatory and fibrotic progression of diabetic nephropathy." (PMID 40969366, 2025). "In conclusion, our study identifies COL1A2, CD163, FN1, and CCL2 as key molecular players involved in fibrosis, immune activation, and inflammatory signaling in diabetic nephropathy." (PMID 40969366, 2025).
esophageal cancer (6 papers, 2011 to 2025). A primary or metastatic malignant neoplasm involving the esophagus. "COL1A2 is a subtype of type I collagen produced by stromal fibroblasts and cancer cells, and previous researchers have identified it as a potential biomarker correlated with immune infiltration in the esophageal carcinoma TME." (PMID 35875097, 2022).
gastric adenocarcinoma (6 papers, 2021 to 2023). "Altogether, our bioinformatics analysis study identified six upregulated DEGs (ADAMTS2, COL10A1, COL1A1, COL1A2, COL8A1, and BGN) between gastric adenocarcinoma and normal tissues based on four different microarray datasets." (PMID 35726219, 2022). "Furthermore, studies have demonstrated the close relation between collagen genes and gastric adenocarcinoma, including COL10A1, COL1A1, COL1A2, and COL8A1." (PMID 35726219, 2022). "After that, we investigated whether the high expression of dual combinations of COL1A1, COL1A2, COL3A1, or COL5A1 exacerbates the outcome of CAF infiltration in stomach adenocarcinoma." (PMID 35739492, 2022).
lung adenocarcinoma (6 papers, 2016 to 2024). A carcinoma that arises from the lung and is characterized by the presence of malignant glandular epithelial cells. "COL3A1 and COL1A2 higher expressed in tumor samples were hub genes in a miRNA–gene interaction network and related to the survival time of lung adenocarcinoma." (PMID 36138770, 2022). "Hsa-mir-145 formed the third regulatory module for lung adenocarcinoma c with lncRNA C1orf220, which ranked second in potential lncRNAs, and mRNAs (COL1A2, COL3A1, SPP1, TIMP1 and CDH1)." (PMID 36138770, 2022). "The expression of COL1A1, COL1A2, and COL3A1, members of the collagen family, is increased in lung adenocarcinomas and is associated with its poor prognosis." (PMID 34326696, 2021). "Our investigation revealed that COL1A1, COL1A2, FAP, and PDGFRA are effective markers for characterizing CAF subgroups in most lung adenocarcinoma datasets." (PMID 39034310, 2024). "Six genes (COL3A1, COL1A2, OGN, COL15A1, ASPN, and MXRA5) and three miRNAs (hsa-miR-29c-3p, hsa-let-7c-5p, and hsa-miR-29b-3p) were related to the survival time of lung adenocarcinoma (LUAD)." (PMID 32300359, 2020).
renal cell carcinoma (6 papers, 2016 to 2025). "Firstly, we determined the expression levels of five constituents (DUXAP8, DUXAP9, miR-29c-3p, COL1A1 and COL1A2) in 20 pairs of clinical cancer tissues and normal tissues of renal cell carcinoma." (PMID 31409759, 2019). "All these findings suggest that pseudogene DUXAP8/DUXAP9-miR-29c-3p-COL1A1/COL1A2 may be a critical signaling pathway in onset and progression of renal cell carcinoma." (PMID 31409759, 2019). "Taken together, amplification of pseudogenes DUXAP8 and DUXAP9 may lead to increase expression of COL1A1 and COL1A2 by competitively binding to miR-29c-3p, resulting in uncontrolled cell proliferation in renal cell carcinoma." (PMID 31409759, 2019). "These bioinformatic analytic findings indicate that pseudogene DUXAP8 and DUXAP9 may fuel onset and development of renal cell carcinoma by targeting COL1A1 and COL1A2 through competitively binding miR-29c-3p." (PMID 31409759, 2019). "Our current results indicated that DUXAP8 and DUXAP9 may act as two key oncogenes in renal cell carcinoma through upregulation of COL1A1 and COL1A2 by competitively binding miR-29c-3p." (PMID 31409759, 2019).
atherosclerosis (5 papers, 2016 to 2025). A disease characterized by the build-up of fatty material and calcium deposition in the arterial wall resulting in partial or complete occlusion of the arterial lumen. "To validate sensitivity towards the known genes implicated in phenotypic switching of SMCs in atherosclerosis, we confirmed that markers of synthetic SMCs (Fn1, Col1a1, Col3a1, Col1a2, Eln, and Vcam1) were elevated in SMCTRAP-AS compared with SMCTRAP." (PMID 38289873, 2024). "The common mechanisms shared in both are linked with atherosclerosis signaling and inflammatory response with at least the following target genes: Tnfrsf12a, Pla2g2f, Il1f9, Col1a1, Col1a2, and Col3a1 in brain, while Tnfrsf12a, SELP, SELE, IL6, and IL1A in myocardium." (PMID 29681850, 2018). "Here, our in vivo data showed that therapeutic sclerostin antibody elevated serum levels of inflammatory cytokines and chemokines, and aggravated AA and atherosclerosis in Col1a2+/G610C.ApoE-/- mice with AngII infusion." (PMID 35966595, 2022). "AngII infusion led to vascular expansion and development of atherosclerosis in aortic arches, vascular expansion and development of AA in suprarenal aortas in Col1a2+/G610C.ApoE-/- mice." (PMID 35966595, 2022). "Together, therapeutic sclerostin antibody elevated serum levels of inflammatory cytokines and chemokines, aggravated AA and atherosclerosis in Col1a2+/G610C.ApoE-/- mice with AngII infusion." (PMID 35966595, 2022). "Methods and Results: Our data showed that sclerostin suppressed inflammatory responses, prevented aortic aneurysm (AA) and atherosclerosis progression in hSOSTki.Col1a2+/G610C.ApoE-/- mice." (PMID 35966595, 2022). "Furthermore, parameters indicating atherosclerosis progression were characterized in Col1a2+/G610C.ApoE-/- mice with AngII infusion." (PMID 35966595, 2022). "The parameters indicating AA and atherosclerosis progression were detected in Col1a2+/G610C.ApoE-/- mice with AngII infusion, after administration of humanized therapeutic sclerostin antibody (Hongmed-Infagen/Creative Biolabs, 25 mg/kg, twice per week) for four weeks." (PMID 35966595, 2022). "Furthermore, Apc001PE showed no influence on the suppressive effect of sclerostin on inflammatory cytokines and chemokines expression, AA and atherosclerosis progression in hSOSTki.Col1a2+/G610C.ApoE-/- mice with AngII infusion." (PMID 35966595, 2022). "Ten key regulated genes (including Pla2g2f, Il1f9, Col1a1, Col1a2, and Col3a1 in the brain, while SELP, SELE, IL6, and IL1A in the myocardium, and Tnfrsf12a in both) are correlative with atherosclerosis signaling and inflammatory response." (PMID 29681850, 2018).
breast tumor (5 papers, 2006 to 2022). "Among the shared upregulated genes in normal breast tissues and breast tumors, the expression of five genes unique to young women aged ≤40 years with BC (i.e., COL1A2, COL5A2, COL5A1, NPY1R, and KIAA1644) significantly affected the OS and RFS of patients with several tumor subtypes." (PMID 35741056, 2022). "We found that the Col1a1 to Col1a2 ratio was 1.2 in mouse normal breast ECM and 2.6 in mouse breast tumor ECM, a more than two-fold increase in Col1a1 chain in the tumor ECM." (PMID 36547361, 2022). "Since metastases from ER-/PR- breast tumors are reportedly less likely to be skeletal compared to those from receptor-positive tumors, the precise importance of COL1A1/COL1A2 upregulation in TNBC remains unclear." (PMID 31139569, 2019).
cardiac valvular EDS (5 papers, 2020 to 2025). "There are three different EDS types associated with pathogenic variants in the COL1A1 or COL1A2 genes: classical EDS with arterial fragility, arthrochalasis EDS, and cardiac valvular EDS." (PMID 40428297, 2025). "Cardiac-valvular EDS is a very rare EDS type as so far only 7 individuals with an age range from 6–65 years have been reported and is caused by bi-allelic loss of function (LOF) COL1A2 variants leading to mRNA decay." (PMID 39629459, 2024). "EDS cardiac-valvular type (OMIM # 225320) is an autosomal recessive disorder and the involved gene is COL1A2." (PMID 37443678, 2023).